TNF (tumor necrosis factor)
Diseases named in the same sentence as TNF in open-access papers (continued):
Sharing a sentence is not in itself a finding about the gene and the disease.
Insulin resistance (continued). "In the context of T2D, IL-6 and TNF-α are known to be upregulated, contributing to insulin resistance, impaired insulin-mediated glucose uptake in peripheral tissues, and endothelial dysfunction in T2D." (PMID 37892970, 2023). "A major effect of TNF-α is the induction of insulin resistance, impairing protein synthesis, glucose uptake, and adequate muscle performance." (PMID 37373124, 2023). "Tumor necrosis factor and expression, as well as insulin resistance and inflammation, are a group of keywords with high frequency, showing high relevance." (PMID 36836694, 2023). "Macrophages in visceral adipose tissue also secrete several proinflammatory factors such as TNFα, monocyte chemoattractant protein 1 (MCP-1), and interleukin (IL)-1β, which have been implicated in the development of insulin resistance." (PMID 37935669, 2023). "The CI, TNF and DEX models caused a relatively extreme insulin resistance phenotype, likely because these were developed for cells overexpressing GLUT4." (PMID 36283703, 2023). "Since gut microbiota affects insulin resistance by decreasing TNF‐ α level in plasma and improving fasting blood glucose level in mice fed a high‐fat diet." (PMID 37181306, 2023). "Most interestingly, it was shown that a HFD promotes certain adipocytes to co-express toll-like receptor 2 (TLR2) and its downstream molecule, TNFα to induce insulin resistance in mice in the presence of free fatty acids (FFA)." (PMID 37445827, 2023). "Higher levels of interleukin 6 (IL-6) and tumor necrosis factor (TNF) α were found in patients with several features of MetS such as central obesity and insulin resistance, when compared to the general population." (PMID 38004150, 2023). "Abnormal increment of TNF-α and IL-6 in adipose tissue leads to insulin resistance in type 2 diabetes whereas production of IFN-γ, IL-1β and TNF in type 1 diabetes cause toxic effects on beta cells." (PMID 36653816, 2023). "Insulin resistance can also induce adipose tissue inflammation to activate and release proinflammatory cytokines such as IL-6 and TNF-α, which induce endothelial dysfunction, leading to albuminuria and impaired renal function." (PMID 37680883, 2023). "Caffeic acid from propolis improved glucose uptake and decreased glucose 6-phosphatase expression in insulin resistance in vitro; it also improved hyperglycemia, glucose tolerance, and hyperlipidemia, and reduced TNF-α expression in vivo." (PMID 37630833, 2023). "It is discovered that serum protein Acrp30 performs a major part in the management of diabetes mellitus, TNF-α is one of the main pro-inflammatory mediators responsible for the insulin resistance." (PMID 36782201, 2023). "TNF-α suppresses the production of glucose transporter type 4 (GLUT4) and induces insulin resistance, which is responsible for chronic inflammation and causes diabetes." (PMID 36768946, 2023). "Targeting TNF-α therapeutically holds immense potential to address insulin resistance and provide interventions to prevent inflammation-induced insulin resistance by suppressing TNF-α production." (PMID 37511225, 2023). "This study demonstrated a significant decrease in TNF‐α and IL‐1β levels, a decrease in insulin secretion, a reduction in insulin resistance symptoms, and an increase in HOMA‐β levels in each intervention group." (PMID 37181308, 2023). "The link between PsA and DM is not fully understood, but TNF-a seems to contribute to the development of insulin resistance." (PMID 37109438, 2023). "An increase in the concentration of plasma CRP, IL-6, and TNF-α are reported in metabolic syndromes, including cardiovascular diseases and insulin resistance." (PMID 38155869, 2023). "In fact, AA induces a pro-inflammatory state, which represents a fertile ground for the development of insulin resistance (IR), especially via a process interleukin-1β (IL-1 β) and tumor necrosis factor-α (TNF-α) dependent." (PMID 37375575, 2023).
Insulin resistance (continued). "Early reports showed that macrophage TNFα contributes to insulin resistance and its deletion alleviates insulin resistance." (PMID 36994095, 2023). "This review discusses the role of pro-inflammatory cytokines, particularly Interleukin-6, tumor necrosis factor-α, and interleukin-8, play a significant role in the induction of insulin resistance in adipose cells." (PMID 38259415, 2023). "CRP is stimulated by IL-1β, TNF-α and IL-6 in the liver, which act together to activate serine and threonine kinases to suppress insulin signal transduction and thus promote insulin resistance." (PMID 37891561, 2023). "These recruited M1 macrophages secrete pro-inflammatory cytokines, including TNF, IL-6, and IL-1β, and oxidative metabolites such as superoxide and nitric oxide (NO), resulting in inflammation and insulin resistance." (PMID 36838843, 2023). "It inhibits the production of cytokines that induce insulin resistance, such as tumor-necrosis factor or IL-6." (PMID 36768715, 2023). "There is also evidence that SOCS3-mediated insulin resistance is involved in the upregulation of mediators (e.g. tumor necrosis factor-α (TNF-α), Interleukin 6 (IL6)) signaling pathways." (PMID 36609306, 2023). "As depicted in this review, in insulin resistance, there is an increase in pro-inflammatory cytokines such as interleukin (IL)-1, IL-6, and tumor necrosis factor (TNF)-α and ROS." (PMID 37629193, 2023). "Tumor necrosis factor-α (TNF) is a potent proinflammatory cytokine involved in regulating immunity/inflammation, programmed cell death, lipid metabolism, insulin resistance, and endothelial function." (PMID 37280310, 2023). "Recently, serum TNF-a was shown elevated in T2DM patients vs controls and in obese vs non-obese diabetic patients, being associated with glycemic control and insulin resistance." (PMID 37529617, 2023). "Phillyrin is a heterocyclic lignan glycoside flavonoid that attenuates TNF α-mediated insulin resistance and accelerated lipolysis by adipocytes." (PMID 36978911, 2023). "TNF-α can induce systemic insulin resistance by inhibiting insulin receptor tyrosine kinase in muscle and fat, suggesting a possible role in metabolic syndrome seen in PCOS." (PMID 37195871, 2023). "During pregnancy, insulin resistance increases, partly due to elevated levels of circulating adipocytokines: TNF-α, resistin, and leptin." (PMID 38069155, 2023). "Pro-inflammatory cytokines like IL-6 and TNF-α, induce insulin resistance by inhibiting the signals of insulin receptors, thereby increasing the risk of type-2 diabetes." (PMID 38155869, 2023). "Phenols, a large class of bioactive molecules, are important for the modulation of T2D and insulin resistance due to their ability to reduce pro-inflammatory cytokines, such as interleukin-1β (IL-1β), interleukin-6 (IL-6), and tumor necrosis factor-α (TNF-α)." (PMID 37108509, 2023). "Based on these data, we propose exposing 3T3-L1 adipocytes to 0.5 nM insulin and 0.5 ng/ml TNF for 14 h as optimal models of insulin resistance induction." (PMID 36283703, 2023). "Here, we measured the levels of inflammatory cytokines in rats by qPCR, including TNF-α, IL-1β, and IL-6, which are key proinflammatory factors in type 2 diabetes and closely related to insulin resistance." (PMID 37072819, 2023). "The interventions increased the RER values, which implied an increase in glucose as a substrate of energy metabolism, likely related to their ability to alleviate insulin resistance by reducing IL-1β and TNF-α levels." (PMID 37693249, 2023). "An elevated amount of adipocytes and the increased production of TNF-α and IL 6 induce insulin resistance." (PMID 38162615, 2023). "Of note, adipose-derived TNF-α and IL-6 are crucial adipokines that suppress adipocyte insulin sensitivity and even lead to insulin resistance by attenuating insulin receptor-substrate 1 (IRS-1), which is a necessary component of insulin signaling." (PMID 37555019, 2023).
Insulin resistance (continued). "Acute brain ischemia has been found to enhance inflammatory pathways, the expression of hepatic TNF-α, and activities of intracellular NF-κB from catecholamine release, which ultimately results in hepatic insulin resistance." (PMID 36777640, 2023). "TNF-α has been demonstrated in many diseases, including osteoarthritis, autoimmune diseases, ankylosing spondylitis, insulin resistance, psoriasis, nephropathy, and cancer." (PMID 37089716, 2023). "Several studies have found that H. pylori upregulates the expression of various inflammatory factors, including C-reactive protein, tumor necrosis factor, various interleukins, and promotes insulin resistance levels." (PMID 36819677, 2023). "It is suggested that TNF‐alpha is the linkage between insulin resistance and beta‐cell dysfunction by altering glucose homeostasis in the liver and pancreas." (PMID 36721851, 2023). "In obese women, increased adiponectin, leptin, human placental lactogen, placental growth hormone and adipokines such as TNFα further exacerbate low grade inflammation and insulin resistance." (PMID 38288471, 2023). "High-level endotoxemia has been found to increase TNF-α and IL-6 concentrations and insulin resistance." (PMID 37009872, 2023). "TNF-α is a pro-inflammatory factor that plays a crucial role in the pathogenesis of insulin resistance." (PMID 36788619, 2023). "On the other hand, adiposity leads to the production of proinflammatory cytokines such as interleukin-6 (IL-6), interleukin 1-β (IL-1β), and tumor necrosis factor-alpha (TNF-α), which are closely related to renal cell dysfunction and insulin resistance." (PMID 37786577, 2023). "For example, NK cells can produce pro-inflammatory cytokines (e.g., IFN-γ, TNF-α, IL-1, IL-6, and IL-12), which can exacerbate hepatic inflammation and promote insulin resistance." (PMID 37361209, 2023). "Our analysis further confirmed the enrichment of TNF-mediated pathway, insulin resistance, and increased ERK signaling along with downregulation of insulin signaling." (PMID 36012331, 2022). "Although leptin, TNF-α, resistin, and adiponectin are all representative adipokines, the first three are positively correlated with insulin resistance and adiponectin is negatively correlated." (PMID 37073221, 2022). "PPE attenuates insulin resistance by down-regulating TNF signaling pathway, activating the PI3K-Akt signaling pathway to suppress glycogen synthesis and gluconeogenesis." (PMID 36079890, 2022). "While in obese mice, the transcription of TNFα and iNOS genes increase, contributing to TNFα-induced insulin resistance." (PMID 35422689, 2022). "In T2DM, as well as in insulin resistance, there is increased production of IL-6, IL-1β, IL-18, tumor necrosis factor (TNF-a), alpha-1 antichymotrypsin and C-reactive protein." (PMID 35453527, 2022). "Studies have shown that postoperative IL-6 and TNF-α values are positively correlated with insulin resistance." (PMID 35711703, 2022). "IL-6 and TNF-α can induce insulin resistance in the liver and adipocytes by reducing the phosphorylation of insulin receptor substrate (IRS) or by inhibiting IRS transcription." (PMID 36235858, 2022). "KEGG enrichment analysis identified apoptosis, cytokine-cytokine receptor interaction, human cytomegalovirus infection, and insulin resistance as over-represented processes, and TNF, NF-κB, IL-17, and HIF-1 as mainly representative signaling pathways." (PMID 35609226, 2022). "Insulin resistance is partly attributed to the dysregulation of adipocytes, which produce and secrete several cytokines called adipocytokines, e.g., tumor necrosis factor-α(TNF-α), adiponectin, leptin, and plasminogen activator inhibitor-1 (PAI-1)." (PMID 35010830, 2022). "We found that phosphorylation of sequestosome-1 was clearly increased under palmitate-induced insulin resistance, compared to the slight increase in TNF-a-induced insulin resistance." (PMID 35055191, 2022).
Insulin resistance (continued). "M1-induced inflammation and subsequent upregulation of the TNF-α/JNK pathway disrupt insulin signaling, causing insulin resistance (IR) in diabetic adipose tissue." (PMID 36477360, 2022). "TNF-α is an important inflammatory mediator released by adipocytes and inflammatory cells that reflect the insulin resistance state." (PMID 35185386, 2022). "IFN-γ and TNFα induce type 1 macrophages (M1 macrophages) accumulation and promote insulin resistance." (PMID 35574038, 2022). "Visceral fat accumulation induces the secretion of pro-inflammatory cytokines, including IL-6, TNF-α, and IL-8, which reduces insulin sensitivity and leads to hyperinsulinemia and even insulin resistance." (PMID 36474704, 2022). "For example, an increase in TNF-α reduces the secretion of adiponectin and promotes insulin resistance by the inhibition of the insulin receptor substrate 1 signaling pathway." (PMID 35956908, 2022). "TNF-α sera levels are dramatically enhanced in subjects with DM, contributing to insulin resistance state." (PMID 35370943, 2022). "Taken together, we found that there are different patterns in canonical pathways and disease relationships between the phosphoproteomes of palmitate- and TNFα-induced insulin resistance." (PMID 35055191, 2022). "This state of insulin resistance is primarily initiated by a rise in maternal and placental anti-insulinergic hormones, including progesterone, cortisol, tumor necrosis factor α (TNF-α), placental growth hormone, and a fall in plasma adiponectin." (PMID 35745174, 2022). "Functional enrichment analysis revealed that differential tsRNAs indirectly participated in MAPK, AMPK, insulin resistance, the TNF signaling pathway, adipocytokine signaling pathway, and other signaling pathways by interacting with target genes." (PMID 36552481, 2022). "We observed increased TNF-α concentrations and insulin resistance, decreased phosphorylation along the signaling pathway, and of course hypoglycemia rather than hyperglycemia." (PMID 36548717, 2022). "The secretion of TNF-α leads to insulin resistance following phosphorylation of serine residues of the insulin receptor substrate-1." (PMID 36292751, 2022). "It reduces the action of adipocytokines such as leptin, TNF-α, and IL-6, as well as oxidative stress, which leads to an improvement of insulin resistance." (PMID 35742443, 2022). "Cytokines released by the adipose tissue, such as interleukin-6 (IL-6) and tumor necrosis factor-α (TNF-α), appear to directly link adiposity with insulin resistance." (PMID 35956404, 2022). "It has been demonstrated that exercise-induced muscle-derived IL-6 exerts anti-inflammatory effects, inhibiting TNF-α, IL-10, and IL-1β activities, and protecting against TNF-induced insulin resistance." (PMID 36430575, 2022). "Moreover, systemic inflammation in patients with psoriasis, including elevated serum proinflammatory cytokines (e.g., TNF-α, IL-17, and IL-23) may contribute to an increased risk of atherosclerosis, hypertension, alteration of serum lipid composition, and insulin resistance." (PMID 36012327, 2022). "One of the many adipokines that are well studied and contribute to the condition of insulin resistance is TNF-α—a pro-inflammatory cytokine." (PMID 35887957, 2022). "The systemic release of inflammatory cytokines such as IL-6 and TNF-α directly contributes to insulin resistance." (PMID 35326098, 2022). "TNF-α is an adipocytokine involved in developing insulin resistance and the pathogenesis of T2DM by disrupting insulin signaling through serine phosphorylation." (PMID 36577761, 2022). "Tumor necrosis factor (TNF) is mainly secreted by macrophages and can induce insulin resistance through inhibition of Insulin receptor substrate 1 (IRS1), tyrosine phosphorylation and G kinase-anchoring protein 1 (GKAP42) degradation in adipocytes." (PMID 36457705, 2022).
Insulin resistance (continued). "In this study, we examined the effects of fatty acids on the reduced expressions and histone acetylation of lipid metabolism-related genes in 3T3-L1 adipocytes treated with insulin resistance induced by tumor necrosis factor (TNF)-α." (PMID 35028437, 2022). "The JNK (c-Jun N-terminal kinase) pathway is also important in insulin resistance and is a part of the signaling cascade of tumor necrosis factor a (TNF-a)." (PMID 35453527, 2022). "In line with this, in preclinical models, the exogenous administration of TNF-α induced insulin resistance, whereas animals deficient in TNF-α receptors were protected against insulin resistance." (PMID 36012327, 2022). "MCP-1 is released into the bloodstream by abdominal WAT, limits insulin-dependent glucose absorption and contributes to insulin resistance along with the increased level of blood TNF-α and IL-6 concentration." (PMID 35954003, 2022). "TNF can induce insulin resistance and synergistically induce vascular endothelial growth factor (VEGF) production with IL1B and IL6 to affect angiogenesis." (PMID 35755045, 2022). "Previous studies have revealed that interleukin-6 (IL-6) and tumour necrosis factor-α (TNF-α) are involved in insulin resistance; therefore, we explored the clinical significance between these insulin resistance-related factors and FFAs." (PMID 35711703, 2022). "The other, TNF-α, is known for wide-ranging effects, among which are the promotion of insulin resistance and of metabolic processes that release the energy necessary for inflammatory reactions to occur at the cellular level." (PMID 36143268, 2022). "As a result, insulin resistance induced by TNF-α was alleviated via the activation of phosphatidylinositol-3 kinase–protein kinase B (PI3K–Akt/PKB) signaling." (PMID 35684249, 2022). "Hypertrophic adipocytes that produce TNF-α and have increased rates of lipolysis due to insulin resistance are characteristics of dysfunctional adipose tissue." (PMID 36552725, 2022). "Quercetin also inhibited TNF-α-mediated inflammation and insulin resistance in human adipose cells in an in vitro study." (PMID 35057501, 2022). "TNF-α is one of the main pro-inflammatory mediators that contribute to the development of insulin resistance in adipocytes and peripheral tissues by inducing low-grade inflammation in those tissues." (PMID 35276970, 2022). "The studied markers predictive of MAC were TNF-α for inflammation and HOMA C-peptide for insulin resistance, and the computed risk for MAC was highest in the presence of hepatic steatosis and hypertension." (PMID 36143268, 2022). "In the obese state, ATM polarization is shifted towards M1 and M1 ATMs, which mainly upregulates monocytes’ chemoattractants, enhances adipocyte lipolysis and induces insulin resistance by secreting TNF-α and IL-6." (PMID 35052852, 2022). "In hypertrophic adipocytes, monocyte-derived macrophages act as early sensors of metabolic changes and produce tumor necrosis factor α (TNFα) and IL-1β, which mediate hepatosteatosis and insulin resistance." (PMID 36505488, 2022). "Herein, we show that mHypoA-2/29 neurons exposed to pro-inflammatory microglial conditioned medium (MCM) showed higher expression of the pro-inflammatory cytokines IL-6, IL-1β, and TNF-α, in addition to developing insulin resistance." (PMID 35883638, 2022). "Peripheral insulin resistance and hyperinsulinemia will increase peripheral free fatty acid levels, and peripheral and central TNF-α levels will also increase, thereby reducing and clearing Aβ through the liver, leading to increased peripheral Aβ levels." (PMID 35401883, 2022). "By inducing the activation of TLR4/NF- κ B signal pathway, LPS upregulates the levels of inflammatory factors such as TNF- α, IL-1 and IL-10, and promotes oxidative stress, resulting in insulin resistance and NAFLD." (PMID 36618372, 2022).